IGHV3-11 (immunoglobulin heavy variable 3-11)
Description:
V region of the variable domain of immunoglobulin heavy chains that participates in the antigen recognition. Immunoglobulins, also known as antibodies, are membrane-bound or secreted glycoproteins produced by B lymphocytes. In the recognition phase of humoral immunity, the membrane-bound immunoglobulins serve as receptors which, upon binding of a specific antigen, trigger the clonal expansion and differentiation of B lymphocytes into immunoglobulins-secreting plasma cells. Secreted immunoglobulins mediate the effector phase of humoral immunity, which results in the elimination of bound antigens. The antigen binding site is formed by the variable domain of one heavy chain, together with that of its associated light chain. Thus, each immunoglobulin has two antigen binding sites with remarkable affinity for a particular antigen. The variable domains are assembled by a process called V-(D)-J rearrangement and can then be subjected to somatic hypermutations which, after exposure to antigen and selection, allow affinity maturation for a particular antigen.
Synonyms: IGHV311; VH
Tractability: Antibody: its Gene Ontology location is reachable by antibodies, with high confidence; UniProt places it where antibodies can reach, with medium confidence; UniProt predicts a signal peptide or a membrane-spanning region.
Gene: Immunoglobulin variable (V) gene on chromosome 14 (106,116,635 to 106,117,204, reverse strand). Ensembl gene ENSG00000211941.
Subcellular location: Secreted; Cell membrane
Pathways (Reactome):
Immune System: Antigen activates B Cell Receptor (BCR) leading to generation of second messengers; CD22 mediated BCR regulation; Classical antibody-mediated complement activation; FCERI mediated Ca+2 mobilization; FCERI mediated MAPK activation; FCERI mediated NF-kB activation; FCGR activation; Fc epsilon receptor (FCERI) signaling; Immunoregulatory interactions between a Lymphoid and a non-Lymphoid cell; Initial triggering of complement; Regulation of Complement cascade; Regulation of actin dynamics for phagocytic cup formation; Role of LAT2/NTAL/LAB on calcium mobilization; Role of phospholipids in phagocytosis
Disease: FCGR3A-mediated IL10 synthesis; FCGR3A-mediated phagocytosis; Potential therapeutics for SARS
Hemostasis: Cell surface interactions at the vascular wall
Vesicle-mediated transport: Scavenging of heme from plasma
Gene Ontology:
Molecular function: antigen binding
Biological process: immune response; immunoglobulin mediated immune response
Cellular component: extracellular region; plasma membrane
Homologues: Paralogues in human: IGHV3-21 (89% identical), IGHV3-48 (87% identical), IGHV3OR16-8 (87% identical), IGHV3-23 (86% identical), IGHV3-74 (86% identical), IGHV3-66 (85% identical), IGHV3OR16-17 (85% identical), IGHV3-20 (85% identical), IGHV3-7 (85% identical), IGHV3-53 (84% identical), IGHV3OR16-10 (84% identical), IGHV3-43 (83% identical), and 65 more.
Diseases named in the same sentence as IGHV3-11 in open-access papers:
IGHV3-11 is named in the same sentence as 1 disease in open-access papers, as found by Europe PMC text mining. Sharing a sentence is not in itself a finding about the gene and the disease.
IGHV3-11 shares sentences with these, for which no sentence is quoted: Alzheimer disease (1 paper).